Y_RNA (Y RNA )
Gene: Miscellaneous RNA gene on chromosome 17 (77,442,109 to 77,442,213, forward strand). Ensembl gene ENSG00000200651.
Homologues: Orthologues: chimpanzee Y_RNA (99% identical), macaque Y_RNA (52% identical). Paralogues in human: RNY1 (82% identical), Y_RNA (82% identical), Y_RNA (81% identical), Y_RNA (80% identical), RNY1P11 (79% identical), Y_RNA (79% identical), Y_RNA (78% identical), Y_RNA (77% identical), Y_RNA (76% identical), RNY1P8 (75% identical), Y_RNA (75% identical), RNY1P10 (74% identical), and 96 more.